ERICH1 (glutamate rich 1)
Synonyms: HSPC319
Tractability: PROTAC: ubiquitination databases record sites on it; its protein half-life has been measured.
Gene: Protein-coding gene on chromosome 8 (614,746 to 738,106, reverse strand). Ensembl gene ENSG00000104714.
Subcellular location (Human Protein Atlas): Nucleoli fibrillar center; Cytosol; Nucleoplasm
Gene Ontology:
Molecular function: protein binding
Genetic constraint (gnomAD): Loss-of-function variants: 53 observed, 36.94 expected, observed/expected ratio (o/e) 1.43, 90% interval 1.15 to 1.79. The synonymous counts are far from expectation, so gnomAD's model fits this gene poorly and the ratio says little. Missense variants: 746 observed, 533.01 expected, observed/expected ratio (o/e) 1.4, 90% interval 1.32 to 1.49. Synonymous variants: 282 observed, 204.78 expected, observed/expected ratio (o/e) 1.38, 90% interval 1.25 to 1.52.
Homologues: Orthologues: chimpanzee ERICH1 (96% identical), macaque ERICH1 (77% identical), pig ERICH1 (51% identical), dog ERICH1 (48% identical), mouse Erich1 (43% identical), rat Erich1 (42% identical), tropical clawed frog erich1 (23% identical), zebrafish erich1 (19% identical).
Diseases named in the same sentence as ERICH1 in open-access papers:
ERICH1 is named in the same sentence as 8 diseases in open-access papers, as found by Europe PMC text mining. Sharing a sentence is not in itself a finding about the gene and the disease. The quoted sentences say what the papers report.
multiple sclerosis (2 papers, 2023 to 2025). A progressive autoimmune disorder affecting the central nervous system resulting in demyelination. "While ERICH1 has been reported to be associated with the risk of multiple sclerosis (MS), MS and MG are two uncommon neurological problems, both of which can affect the nervous system." (PMID 37051601, 2023). "In PPMI stage V06 (24 months) DE circRNA, ERICH1 was found in two other neurological diseases, which are myasthenia gravis and multiple sclerosis." (PMID 41327336, 2025).
depression (1 paper, 2026). "Our results showed significant causal genetic evidence for injury-associated DNAm changes at cg24526596 (DLGAP2), cg00157656 (ERICH1), cg12317217 (PCDHA2), and cg12661624 (PTPRN2) on depression onset." (PMID 41995537, 2026). "The present study provided genetic evidence supporting the causal role of DNAm in the onset of depression or PTSD after injury and identified DLGAP2, ERICH1, PCDHA2, and PTPRN2 as the candidate genes worthy of further exploratory investigation." (PMID 41995537, 2026).
ERICH1 also shares sentences with these, for which no sentence is quoted: cancer (1 paper); fragile X syndrome (1); myasthenia gravis (1); nervous system tumor (1); neurological diseases (1); tumor (1).